BRAF (B-Raf proto-oncogene, serine/threonine kinase)
Diseases named in the same sentence as BRAF in open-access papers (continued):
Sharing a sentence is not in itself a finding about the gene and the disease.
melanoma (continued). "In this multicenter, double-blind, phase III study, 418 patients with previously untreated, unresectable, stage III/IV, wild-type BRAF melanoma were randomly assigned 1:1 to receive nivolumab or dacarbazine, with OS as primary endpoint." (PMID 34447613, 2021). "The combination of the BRAF inhibitor dabrafenib and the MEK inhibitor trametinib was the first BRAF/MEK inhibitor combination to be approved for the treatment of advanced melanoma in the USA in 2014, and in the EU in 2015." (PMID 33804800, 2021). "Nine months later, she presented with recurrent metastatic BRAF-wildtype melanoma with nodal and pulmonary involvement." (PMID 34746007, 2021). "Results in melanoma with this approach have been very promising with a dual inhibition being superior to BRAF-inhibition on its own, significantly increasing response rates, PFS, and OS." (PMID 33916289, 2021). "Although we did not evaluate the response of healthy tissue, this approach did allow us to detect differences in the mutagenicity of a single UVB exposure among melanomas expressing endogenous levels of mutant NRAS or BRAF." (PMID 34210801, 2021). "With the aim of investigating the potential DDI between ARAs and vemurafenib in BRAF-mutant melanoma patients, a large retrospective analysis from 4 phase III trials was conducted." (PMID 33546228, 2021). "In the case of V-raf murine sarcoma viral oncogene homolog B1 (BRAF)-mutant melanomas, highly selective BRAF and mitogen-activated protein kinase (MEK) inhibitors have shown to improve patient survival." (PMID 33430068, 2021). "Our data do not support increased aggressiveness and higher responsiveness to CII of NRAS-mutant melanoma with respect to NRAS/BRAF wild type." (PMID 33530579, 2021). "Similar to chemotherapy-resistant cells, melanoma cells resistant to the BRAF inhibitor vemurafenib have increased levels of ROS, which can be additionally increased by using the histone deacetylase inhibitor vorinostat." (PMID 33525637, 2021). "PSAT1 is a critical component of BRAF inhibitor resistance of pancreatic cancer, melanoma, and NSCLC." (PMID 33526036, 2021). "Three BRAF V600 mutant inhibitors, namely, vemurafenib, dabrafenib and encorafenib, have been approved in combination with MEK inhibitors as a treatment regimen for patients with advanced melanoma harboring BRAF V600 mutants." (PMID 33917428, 2021). "Full OS data are not yet available but it appears as though the plateau on the OS will be less than 50%, well below the 5-year OS plateau of 60% seen in patients with BRAF-mutant melanoma treated with nivolumab plus ipilimumab in the Checkmate 067 study." (PMID 33827575, 2021). "Here, we expanded our work to confirm our previous results of SIRT3 knockdown in BRAF-mutant human melanoma cell line G361." (PMID 33937086, 2021). "Previous studies demonstrate that CDK4/6 inhibitors reduced melanoma cell growth and synergized with BRAF and MEK inhibitors." (PMID 32413516, 2020). "Pharmacologic inhibition of mutant BRAF in melanoma cells activates melanocyte-specific gene expression." (PMID 32151278, 2020). "As a proof of concept, we evaluate the performance of the metrics in two BRAF-mutant melanoma cell lines exposed to a range of targeted drugs which have been tested or proposed to be studied in combination with standard of care BRAF and MEK kinase inhibitors." (PMID 32084135, 2020). "In vivo, this combination was also successful in inhibiting tumor growth for BRAF-V600E melanoma, when ABT-199 was administered at an increased frequency of three times per week." (PMID 32764384, 2020). "ZSTK474 and/or MK-2206 and/or KU-0063794 also induced apoptosis in both BRAFV600E and BRAF WT melanoma cell lines." (PMID 32085796, 2020). "In this short report we show that the non-nucleoside RTI, SPV122 in combination with MAPKi strongly inhibits BRAF-mutant melanoma cell growth, induces apoptosis, and delays the emergence of resistance to target therapy in vitro." (PMID 32933538, 2020).
melanoma (continued). "Because of the success of target therapies, identifying patients with BRAF-mutant melanomas is paramount." (PMID 32429485, 2020). "For example, Y-27632 was reported to inhibit mouse B16 melanoma cell growth, but we recently reported that Y-27632 actually enhances the growth of BRAF-mutant human melanoma cells." (PMID 32843583, 2020). "The main objective of this study was to describe characteristics of LVEF‐D in melanoma patients treated with BRAF and/or MEKis." (PMID 32056395, 2020). "Anti‐PD‐1 monotherapies (aPD‐1) and BRAF/MEK inhibitors (BRAF/MEKi) changed the BRAF‐mutant advanced melanoma treatment landscape." (PMID 32871054, 2020). "The compound of thiazole benzenesulfonamides overcomes BRAF inhibitor resistance in melanoma via triggering ER stress-induced cell death." (PMID 32522979, 2020). "BRAF inhibitors revolutionised the management of melanoma patients and although resistance occurs, there is a subgroup of patients who maintain durable disease control." (PMID 33139839, 2020). "This was a retrospective study of BRAF‐mutant advanced melanoma patients who initiated 1L aPD‐1 or BRAF/MEKi in the US Oncology Network between 1 January 2014 and 31 December 2017, followed through 31 December 2018." (PMID 32871054, 2020). "Selective inhibitors of RAF kinases, such as vemurafenib, regorafenib, and dabrafenib, have recently been introduced into clinical practice, and BRAF inhibitors have proved to be highly effective for the treatment of BRAF-mutant melanoma." (PMID 32066410, 2020). "We applied a machine-learning method, based on MRI radiomics features for noninvasive characterization of the BRAF status of brain metastases from melanoma (BMM) and applied it to BMM patients from two tertiary neuro-oncological centers." (PMID 32313236, 2020). "The combination of BRAF and MEK inhibitors now forms the backbone of advanced BRAF-mutated melanoma treatment." (PMID 33092131, 2020). "Vemurafenib, a selective BRAF inhibitor, has been approved by FDA for the treatment of patients with metastatic BRAFV600E-mutated melanoma, as it owns dose-dependent anti-proliferative and apoptotic effects in melanoma cells." (PMID 33292371, 2020). "The results convey that FKB inhibited cell viability, B-Raf proto-oncogene, serine/threonine kinase (BRAF)/extracellular signal-regulated kinase (ERK) expression in human melanoma cells." (PMID 33053749, 2020). "Several BRAF inhibitors have been developed and approved for the treatment of melanoma and other BRAF-mutant tumors." (PMID 33036192, 2020). "In particular, we have previously demonstrated that melanoma cells treated with BRAF inhibitors upregulate the cell surface receptor Neuropilin-1 (NRP1), which elicits an EGFR-dependent mechanism of adaptive resistance to therapy." (PMID 32784465, 2020). "In a phase III clinical of patients with advanced melanoma harboring the BRAFV600E mutation, the combination of BRAF and MEK inhibitors (dabrafenib plus trametinib) increased the 3-year relapse-free survival rate compared to placebo treatment (58% vs. 39%)." (PMID 32626712, 2020). "For patients with BRAFV600E/K mutant melanoma, significant efficacy has been observed with the combination of a BRAF inhibitor and a MEK inhibitor, with a response rate of ~76%8." (PMID 32504051, 2020). "MAPK inhibitors, such as BRAF inhibitors and MEK inhibitors, which are currently used in combination, demonstrated their high efficacy to treat BRAF-mutant melanoma, however an acquired resistance undoubtedly develops." (PMID 33339398, 2020). "Since immunotherapy resistance is an increasing therapeutic challenge in cancer, including melanoma, we set up an experimental system to model T cell resistance, similar to what we and others have done successfully previously to study BRAF + MEK resistance." (PMID 32770055, 2020). "We demonstrated previously that PMCA4b over-expression decreased migration and metastatic activity of BRAF mutant A375 melanoma cells." (PMID 32414111, 2020).
melanoma (continued). "These agents demonstrated favorable results in trials of treatment‐naïve patients with unresectable BRAF‐mutant melanoma." (PMID 32871054, 2020). "Aberrant signaling or hyper activation of MAPK pathway has been shown in many tumors including melanomas, non-small cell lung cancer (NSCLC), pancreatic and colorectal cancers, chiefly due to mutations in RAS and BRAF proto-oncogenes." (PMID 33738242, 2020). "The analog 6-thio-dG has also been reported to have promising antitumor activity in BRAF as well as checkpoint inhibitor-resistant melanomas." (PMID 32674474, 2020). "BRAF inhibitors for treatment of melanoma are effective transiently, however, most patients develop resistance." (PMID 32373541, 2020). "Similar to other malignancies, knockdown of MCL-1 sensitizes melanoma cells to various treatments, including BRAF or MEK inhibitors." (PMID 33308268, 2020). "The exposure of melanoma cells to BRAF and MEK inhibitors induced the upregulation of histone methyltransferases (SETDB1 and SETDB2), as well as the overexpression of histone demethylases (KDM6A, KDM6B, KDM1B, JARID1A, JARID1B)." (PMID 32605090, 2020). "Recent studies show that microRNAs not only control key pathways leading to the development and progression of melanoma but also are capable of influencing the development of resistance to BRAF inhibitors." (PMID 32555626, 2020). "This suggests a direct interaction and functional correlation between NOS and NOX, BRAF/NRAS mutations, melanoma progression, and drug-resistance." (PMID 32850409, 2020). "This is the case of BRAF V600E, which is present in melanoma and colorectal adenocarcinoma patients." (PMID 32239503, 2020). "Accordingly, overexpression of miR-514a increases survival of vemurafenib-treated BRAF(V600E) melanoma cells." (PMID 32604720, 2020). "The most common drivers of melanoma proliferation are NRAS and BRAF mutations, constitutively activating the ERK MAPK pathway in about 80% of tumors." (PMID 32531927, 2020). "It was demonstrated also that BRAF and NRAS mutations positively regulate MMP-14 gene expression enhancing tumor growth and melanoma invasiveness in vivo." (PMID 32392801, 2020). "The finding that miR-125a is up-regulated in tissues of BRAFi-treated melanoma patients as compared to tumor samples excised before BRAF-treatment, allowed Authors to propose the use of anti-miR-125-a for preventing or overcame BRAFi resistance." (PMID 32604720, 2020). "The benefit of these combinations, specifically anti-PD1 and MEKi in BRAF wild-type melanoma patients, needs to be prospectively studied." (PMID 32585901, 2020). "In conclusion, our work shows that acquired resistance to BRAF inhibitors in BRAF-mutant melanoma is characterised by lower glycolytic and bioenergetic metabolism." (PMID 31819183, 2020). "It was proposed in our previous publication that CAP and SN co-effectively inhibited BRAF gene expression in G-361 melanoma cells and hence repressed the mentioned survival pathways which lead to cell death." (PMID 32178401, 2020). "For instance, specific secretion of HGF and neuregulin (NRG)-1 by fibroblasts upon exposure to vemurafenib -a BRAF inhibitor-was reported in melanoma." (PMID 33553157, 2020). "Analysis of our cohort of 95 melanoma PDX, several of which were derived from BRAF inhibitor-relapsed tumors, showed that NGFR expression levels were significantly higher in the BRAF inhibitor-resistant melanomas." (PMID 32770055, 2020). "Sumimoto and collaborators showed that in BRAF-mutant melanomas Tregs are activated and suppress the antitumor function of T lymphocytes." (PMID 33036192, 2020). "A downregulation of MITF in melanoma cells has been related to an invasive/poorly proliferative phenotype, increased plasticity and acquired therapy resistance to BRAF inhibition." (PMID 33167306, 2020). "For example, two of the most frequent driver mutations in melanoma are the NRAS Q61R and the BRAF V600E mutations." (PMID 33207206, 2020).
melanoma (continued). "This was concordant with previous studies describing that MITFlow melanoma cells are intrinsically resistant to BRAF inhibitors." (PMID 32245160, 2020). "This study focused on identification and validation of drug enhancer hits in the context of glycolysis as a way to identify new candidate drug targets to improve response to BRAF targeted therapies in melanoma patients." (PMID 33046726, 2020). "In summary, our work shows that Galectin-1 triggers an autocrine NRP1-dependent pathway in melanoma cells, driving adaptive refractoriness to BRAF inhibitors." (PMID 32784465, 2020). "Intermittent on-and-off dosing schedules have been shown to double the time of response of melanoma cells to BRAF inhibition." (PMID 32595946, 2020). "The current anti-cancer strategies are based on the inhibition of a specific target playing a key role in tumor development [example: EGFR (lung cancers); HER2 (breast cancers); BRAF (melanoma)]." (PMID 32775327, 2020). "Analysis of biopsies from patients with BRAF-mutant melanoma has shown that BRAF inhibitor treatment increases expression of markers of T-cell cytotoxicity, such as perforin and granzyme B." (PMID 32645969, 2020). "Subsequently, the combination of BRAF inhibitors plus MEK inhibitors seemed to further improve the outcome in terms of Overall Survival (OS) among treated patients and combination therapy became the standard of treatment for BRAF mutant melanoma." (PMID 32695793, 2020). "More recently, between 2018 and December 2019, FDA and EMA released the approval for prescribing BRAF and MEK inhibitors in high-risk resected (stage III) melanoma patients." (PMID 32695793, 2020). "BRAF mutations are more frequent in SSM and in melanomas located on the trunk; in fact, in our study, although we only had 3 cases with SSM, all had BRAF mutations." (PMID 32775409, 2020). "Although treatment strategies based on inhibiting the BRAF kinase in melanomas have shown initial promise, resistance to this treatment develops almost invariably." (PMID 34589668, 2020). "BRAF(+) melanoma is known for shorter OS in patients with stage IV disease, shorter than in those with BRAF WT disease." (PMID 32605090, 2020). "Nelfinavir sensitized BRAF-mutated melanoma cells to MEK inhibitors and BRAF inhibitors via SMAD-mediated downregulation of PAX and MITF, and decreased phosphorylation of ERK during combination with inhibitors of MEK or BRAF." (PMID 33228205, 2020). "High-resolution mass spectrometry identifies massive changes in the phosphoproteome of BRAF mutant melanoma cells after the acquisition of drug resistance." (PMID 32466585, 2020). "What’s more, the up-regulation of A20 conferred the acquired resistance to Vemurafenib in BRAF-mutant melanoma." (PMID 32968045, 2020). "For BRAF wild-type melanomas, the therapeutic approach is the use of first-line therapy immune checkpoint inhibitors (ICI) with antibodies against PD-1/PD-L1, either alone or in combination with anti CTLA4 antibodies." (PMID 32178301, 2020). "Targeted therapy of patients with BRAF-mutated melanoma with either BRAF inhibitors or a combination of BRAF and MEK inhibitors has demonstrated a great success for the treatment of melanoma patients." (PMID 32719412, 2020). "Firstly, BRAF inhibitors help restore an immune-stimulatory microenvironment in BRAF-mutant melanomas." (PMID 32645969, 2020). "Dabrafenib (Tanfinlar®) is a BRAF kinase inhibitor approved by the U.S. FDA for BRAF V600E melanomas." (PMID 31748891, 2020). "The phase II COMBI-MB trial evaluated the efficacy of dabrafenib plus trametinib in patients with BRAF V600E positive melanoma with asymptomatic brain metastases." (PMID 33042847, 2020).
melanoma (continued). "The same study showed that TERT ectopic expression alone was sufficient to rescue the growth of melanoma cells expressing BRAF-targeting short hairpin RNA." (PMID 33024276, 2020). "A new compound, FL3, was demonstrated to overcome BRAF-inhibitor resistance in murine models of melanoma." (PMID 32517051, 2020). "Resistance to BRAF/MEK inhibitors is a major impediment to long-term survival for patients with BRAF-mutant melanomas." (PMID 33122628, 2020). "A combination of a MEK inhibitor with a mutant BRAF inhibitor effectively increased the melanoma survival rate in a randomized clinical trial 15-17." (PMID 32863956, 2020). "The loss of the CDKN2A sequence also co-operates with the BRAF and NRAS oncogenes to promote melanoma development." (PMID 33076392, 2020). "The genetic changes also contribute to the increased cytoprotective autophagy seen in BRAF inhibitor-resistant melanoma cells, allowing tumor cell proliferation to continue unchecked." (PMID 33003483, 2020). "Treatment of advanced melanoma has advanced in recent years, as the role of certain oncogenes (BRAF/NRAS/KIT) in disease pathogenesis has been further elucidated." (PMID 32545409, 2020). "Inhibition of the RAF-MEK-ERK pathway in BRAF mutant melanoma cells led to ZFP36 S218/S222 dephosphorylation and subsequent binding to NOXA mRNA, triggering its decay." (PMID 31988312, 2020). "Areas currently under investigation include ICI therapy in the adjuvant setting and also ICI therapy in combination with BRAF/MEK inhibition for BRAF-mutant melanoma." (PMID 32545409, 2020). "We identified a unique role for AURKB in melanoma, through the mediation of both the BRAF/MEK/ERKs and PI3-K/AKT pathways." (PMID 32863956, 2020). "BRAF p.S607P and p.V600M have been reported in melanoma, while BRAF p.A598T has been identified in non small cell lung cancer." (PMID 32059434, 2020). "Dabrafenib and trametinib combination therapy is approved for the treatment of patients with BRAF V600E positive tumors including melanoma and lung cancer." (PMID 32131760, 2020). "Our study cohort was selected from patients who underwent routine BRAF status testing and was thus skewed towards advanced melanoma patients." (PMID 32843682, 2020). "MiR-204 and miR-211 play a role for targeted therapy of melanoma as they can contribute to the resistance of melanoma cells to treatment with the BRAF inhibitor Vemurafenib." (PMID 31906510, 2020). "The MAPK pathway is involved in T-cell receptor signalling, and interference with the pathway by BRAF inhibitors has beneficial effects on the tumour microenvironment and anti-tumour immune response in BRAF-mutant melanoma." (PMID 32645969, 2020). "In melanoma, the CCND1 amplification rate is 11%, and this increases to 17% in BRAF V600E melanoma, suggesting a critical role for CCND1 in BRAF-mutated melanoma patients." (PMID 32413516, 2020). "In experiments in vitro, BRAF inhibition blocks melanoma growth and stimulates apoptosis, while, in vivo, reduced tumor formation is observed in mouse models." (PMID 33036192, 2020). "Firstly, ERK and ribosomal protein S6 kinase A (RSK), two downstream kinases of MAPK signaling, have been shown to phosphorylate and inhibit the upstream activator of AMPK, LKB1, and thereby block the activation of AMPK by LKB1 in BRAF(V600E)-driven melanoma." (PMID 32807225, 2020). "It is now well known that BRAF inhibition alone in melanoma can be overcome by many different mechanisms of resistance, some of which encompass downstream reactivation of MAPK pathway." (PMID 33036192, 2020). "The suppression of MAPK pathway by targeting BRAF has achieved revolutionary therapeutic progress in BRAF-mutant melanoma." (PMID 32968045, 2020). "The V600E alteration is the most prevalent present in 80–90% of BRAF mutant melanomas, in 50% of BRAF mutant lung adenocarcinomas, and in 90% of BRAF mutant colorectal cancers." (PMID 33081092, 2020).